ALK (ALK receptor tyrosine kinase)
Diseases named in the same sentence as ALK in open-access papers (continued):
Sharing a sentence is not in itself a finding about the gene and the disease.
tumor (continued). "TSR-011 is a dual ALK and tropomyosin-related kinase (TRK) inhibitor, active against ALK inhibitor resistant tumours in preclinical studies." (PMID 31217479, 2019). "In tumor samples, 18 out of 24 ALK− ALCL samples had PD-L1 expression, compared to 18 out of 36 ALK+ ALCL tumor samples, and in both groups PD-L1 expression was correlated with STAT3 activation." (PMID 31684088, 2019). "In a phase III trial (KEYNOTE-024) comparing pembrolizumab with platinum-doublet chemotherapy in chemo-naïve patients whose tumor was positive for PD-L1 ≥ 50%, patients who had EGFR or ALK alterations were excluded." (PMID 31049758, 2019). "Additionally, results support a role for ALK in generating mesenchymal CTCs, suggesting that CTCs with a unique ALK rearrangement and a mesenchymal phenotype may result from the clonal selection of tumor cells that have acquired the potential to metastasize, such as cancer stem cells." (PMID 30959764, 2019). "Rearrangements involving the anaplastic lymphoma kinase (ALK) gene with the striatin (STRN) gene have been described, which constitutively activate ALK kinase, inducing tumor formation in nude mice." (PMID 31717449, 2019). "Here, the authors have found PIM1 overexpression decreases sensitivity to ALK inhibitors in NB and combined ALK and PIM1 inhibition enhances anti-tumour efficacy in vitro and in PDX models." (PMID 31780656, 2019). "To explore different fusion genes in a single assay and to detect gene partners engaged in ALK (anaplastic lymphoma kinase) or ROS1 fusion, we evaluated two commercially available targeted RNA‐sequencing assays in a set of 37 tumor samples." (PMID 31651105, 2019). "The group demonstrated a significant upregulation of several miR-17-92 cluster members in ALK-positive ALCL from transgenic mouse models and primary tumor tissues." (PMID 31052302, 2019). "Similar to ALK and ROS1 rearrangement, fusions of NTRK1, NTRK2, and NTRK3 are actionable drivers of tumor growth." (PMID 31023335, 2019). "However, the mean expression levels of circulating miR-504 in ALK-positive patients (11.41 for miR-191 normalised data; 15.38 for miR-16 normalised data) were clearly lower than in EGFR-mutated subjects (13.24 and 17.01, respectively), which is consistent with the trend observed in tumour tissue." (PMID 30953094, 2019). "Inhibition of the ALK tyrosine kinase and its subsequent signal transduction pathway with specific TKI's results in tumor growth arrest, improved clinical response and a survival benefit in ALK-positive NSCLC as compared to WT NSCLC." (PMID 30416687, 2018). "In case 1, vimentin was expressed in both tumor tissues and CTCs, suggesting that EMT led to off-target resistance to ALK inhibitor." (PMID 29844868, 2018). "Out of 712 patients, 515 (72%) had tumor tissue available for molecular testing; 37% (188/515) of tumors were analyzed using NGS methods, while 59% (306/515) were tested only for EGFR and ALK." (PMID 29854298, 2018). "It therefore was approved for first-line treatment of patients with mNSCLC whose tumors have high PD-L1 expression (tumor proportion score (TPS) ≥ 50%) and wild type of EGFR or ALK genes." (PMID 30159341, 2018). "However, neither ALK gene amplification nor mutation was detected in the graft tumor." (PMID 29755689, 2018). "The apparently higher sensitivity to ALK inhibitors of ALCL and IMT tumors likely reflects a stronger dependency on ALK signaling and/or a lower level of tumor heterogeneity than in ALK-rearranged NSCLC." (PMID 29495603, 2018). "The combinatorial inhibition of ALK and HDAC8 also decreased tumor growth in an in vivo zebrafish xenograft model." (PMID 29515255, 2018). "The results from the screen uncovered MYCBP as a target in sensitizing ALK+ NSCLC to crizotinib, implicating the MYC signaling axis as critical in this tumor type." (PMID 29507657, 2018).
tumor (continued). "ALK is almost exclusively co-amplified with MYCN, consistent with the proximity of these genes at 2p23-24 and therefore tumours harbouring ALK amplification tend to afford a poor prognosis." (PMID 29642598, 2018). "We next investigated if ALK is involved in transcriptional regulation of MYC, as demonstrated in other ALK-activated tumor types." (PMID 29507657, 2018). "Although the tumor histology varied widely in this study, the median progression-free survival for patients harboring rearrangements in NTRK1/2/3, ROS1, and ALK is 19.0 months." (PMID 29617282, 2018). "PF-2341066, a small molecule inhibitor of c-MET and ALK, has been administered in ALCL with inhibition of tumor progression and apoptosis, as well as other c-MET inhibitors (e.g., SU11274 and PHA665752)." (PMID 29854308, 2018). "Regarding ALK+ALCL, we are aware of a publication in which tumor-propagating cells were identified based on their high Hoechst-efflux ability." (PMID 29609590, 2018). "Elevated concentrations of IL-10 in the sera of children with ALK-positive ALCL before treatment correlated with the presence and quantity of circulating tumor cells." (PMID 29642597, 2018). "MYCN and ALK copy number assessment from plasma at diagnosis could also identify patients with possible subclonal amplifications, and this analysis should accompany tumor biopsy analyses to test its clinical predictive power for possible future use in treatment stratification." (PMID 29156716, 2017). "Immunohistochemical staining revealed that the large-sized tumor cells were positive for CD20, PAX-5, MUM-1 and BCL-2, and were negative for CD3, CD5, CD43, CD10, CD23, CyclinD1, CD138, CD30, ALK, CD56, MPO, S-100, TTF-1, thyroglobulin and calcitonin." (PMID 28841887, 2017). "Our ddPCR protocol accurately detected the ALK normal diploid status and amplified MYCN status of the xenograft tumor from mouse blood plasma." (PMID 29156716, 2017). "Combinational treatment with the c-Met/ALK inhibitor crizotinib and gemcitabine significantly reduced PDAC CAM tumor growth." (PMID 28304379, 2017). "Studying the correlation between ALK expression and survival in a larger MCC tumor cohort would be of future interest." (PMID 28359267, 2017). "In murine engraftment models of ALK(−) ALCL, anti-miR-155 molecules reduced tumor growth, raised tumoral levels of cleaved caspase-3 and increased SOCS1 expression, leading to the suppression of STAT3 signaling." (PMID 28771164, 2017). "Furthermore, the activation of tumor-suppressive miRNA and the inhibition of oncogenic miRNA may have the potential to provide a fundamentally new approach for the development of therapeutics for many cancers, including ALK(+) ALCL." (PMID 28771164, 2017). "The expression of anaplastic lymphoma kinase (ALK), CD5, CD30, and C-Myc in tumor specimens from 109 patients was detected using IHC, and Epstein–Barr virus (EBV)-encoded RNAs (EBERs) were detected using fluorescence in situ hybridization." (PMID 29246182, 2017). "They concluded that Ventana ALK D5F3 IHC was superior to ALK-FISH on small biopsies and FNA to predict tumour response and survival to crizotinib for advanced NSCLC patients." (PMID 28887531, 2017). "The ALK gene was evaluated using IHC and FISH in 78 paired specimens (primary tumor site and paired metastatic lymph nodes)." (PMID 29312572, 2017). "Therefore, it is important to keep in mind that even for the known variants of ALK fusion genes, the biological function is not known for all variants, and that no information is available on the homogeneity of ALK fusion variants within a single tumor." (PMID 28696381, 2017). "Therefore, mutated ALK alleles may not be selected during the branching evolution of tumor development." (PMID 29296183, 2017). "Patients who have genomic tumor aberrations, such as EGFR or ALK, and are receiving an approved EGFR- or ALK-directed therapy should have disease progression prior to receiving nivolumab." (PMID 28090370, 2016).
tumor (continued). "AP-MS has been successfully used to discover novel TKFs in NSCLC (ALK and ROS1) and rare TKFs in other tumor histotypes." (PMID 26943776, 2016). "Another ALK aberration, the gene copy number gain (CNG), has been identified in several tumor types and significantly correlated with poor prognosis and/or advanced disease status." (PMID 27561692, 2016). "The true therapeutic benefit of novel molecules targeting the mutant ALK fusion protein in NSCLC relies on identifying the right patient population for treatment, and on detecting the emergence of tumor resistance." (PMID 26993609, 2016). "Tumor tissues were analyzed for ALK-CNG by FISH, and patients were divided in 3 groups/patterns on the basis of ALK signals: disomic [Pattern A], 3–7 signals [Pattern B], >7 signals [Pattern C]." (PMID 27561692, 2016). "Here, the patient’s primary tumor tissue sample was borderline positive on FISH; the percentage of ALK rearrangements fell in the 15 to 20 % range." (PMID 26968843, 2016). "Immunohistochemically, tumor cells are characterized by CD30, ALK, CD5, TIA-1, Granzyme B, EMA positive staining, and CD2, CD3, CD7, CD4, CD8, CD20, CD79a negative staining." (PMID 27612448, 2016). "Together, the data demonstrates that the ALK inhibitor AZD3463 can significantly suppress the viability of ALK WT and mutant NB cell lines and lead to tumor cell death in a dose-and time-dependent manners." (PMID 26786851, 2016). "We identified crizotinib, a MET and ALK inhibitor, as a potent inhibitor of NF2-null Schwann cell proliferation in vitro and tumor growth in vivo." (PMID 27363027, 2016). "We examined EGFR and ALK expression in the tumor cells and the effect of erlotinib and crizotinib on the phosphorylation of EGFR and ALK by Western blotting." (PMID 27070423, 2016). "Of the 9 ALK FISH positive patients who received crizotinib treatment, 8 (88.9%) patients exhibited tumor regression." (PMID 26789109, 2016). "Previously, a study with a murine ALK positive NSCLC model in which the ALK kinase inhibitor TAE684 was administered, a substantially diminished tumor metabolic activity was detected within 24 hours of starting therapy." (PMID 27137772, 2016). "It is clear however, that treating ALK and ROS1 mutant tumours with the appropriate targeted agents substantially improves patient’s outcome." (PMID 27350784, 2016). "Baseline 18F-FDG PET and CT tumor response measurements with PERCIST and EORTC criteria and progression-free survival per patient with ALK positive NSCLC." (PMID 27137772, 2016). "Overall, these data demonstrate that many MVPs are shared between the tumor samples in comparison to normal CD3+ T cells and unique DNA methylation characteristics between ALK+ ALCL and ALK− ALCL are mainly based on hypomethylated MVPs in ALK+ tumors." (PMID 27705804, 2016). "The remaining 10 ARMS and 28 ERMS were described as disomic for the ALK gene, with an average of FISH signals of 2-2.4 (percentage of tumor cells with acquisition 2–11%) and 2–2.7 (percentage of tumor cells with acquisition 1–57%), respectively." (PMID 27385213, 2016). "We found that ground-glass opacity at the main tumor was significantly more common among EGFR-positive patients, compared to ALK-positive patients (p = 0.009)." (PMID 27518729, 2016). "The goal of this paper is to describe metabolic responses on crizotinib in ALK positive NSCLC patients and compare PET and CT assessments with different tumor response criteria." (PMID 27137772, 2016). "In tumor samples analyzed by FISH, a threshold of 15% ALK- rearranged cells is typically used to define ALK-positive patients." (PMID 27739521, 2016). "NSCLC and IMT tumours harbouring these 2 types of mutation, however, do not display significant changes in ALK constitutive activity and, therefore, might be positively selected in vivo only in the presence of ALK inhibitors." (PMID 25874976, 2015).
tumor (continued). "Recent clinical studies have reported a promising therapeutic impact of crizotinib, an ATP-competitive inhibitor of ALK/MET activity, in the treatment of ALK- and/or MET-positive tumours." (PMID 26445453, 2015). "We confirmed also the down-regulation of miR-29a in ALK+ ALCL cell lines, which was recently shown to upregulate the antiapoptotic protein MCL1 contributing to tumor cell survival." (PMID 25688981, 2015). "Both crizotinib and entrectinib inhibited the phosphorylation of ALK and its downstream signal molecules, including ERK1/2 and AKT from this EML4-ALK rearranged colon patient tumor derived cell line." (PMID 26172300, 2015). "Only one analyzed tumor, a LCNEC case, showed a candidate ALK gene fusion event (DNBL-ALK) based on NGS data, however just with the minimum number of reads required for reporting." (PMID 26124082, 2015). "Employing an independent cohort of ALCL patient tumours, we show that miR-155 expression is significantly higher in ALK− (n = 11) as compared to ALCL ALK+ tumours (n = 15, p < 0.001) or normal lymph node and CD3+ T cells, corroborating our previous results." (PMID 25820993, 2015). "The present patient with ALK rearrangement-positive NSCLC showed pronounced and rapid regression of tumor only 6 months after starting crizotinib." (PMID 25889062, 2015). "In addition, if ALK amplification in the absence of a secondary mutation causes crizotinib resistance, a high level of amplification may result in the resistant tumor." (PMID 25941796, 2015). "Of the 36 patients with ALK-rearranged NSCLC, a mass and a nodule were identified in 17 (47.2%) and 16 (44.4%), respectively, indicating that more than 40% had a small-sized tumor." (PMID 24403104, 2014). "The tumor cells are positive for CD30 on the cell membrane and in the Golgi region, and usually ALK positive." (PMID 25183396, 2014). "ALK rearrangements were detected in 3.85%, 4.31%, 5.72% and 12.39% of NSCLC patients with tumor stage of I (30 articles: 199/5168), II (25 articles: 50/1161), III (27 articles: 119/2080) and IV (28 articles: 214/1727), respectively." (PMID 24959902, 2014). "Pre-clinical studies involving HSP90 inhibitors in ALK+ NSCLC led to decreased ALK fusion protein levels in vitro, and led to tumor regression in in vivo models." (PMID 25101240, 2014). "Moreover, Myc endogenous expression was strongly upregulated in orthotopic JoMa1-ALK tumors or their derived cell lines as a result of ALK activation, and both ALK and Myc activities were required to maintain in vitro tumorigenic capacities of tumor-derived cell lines." (PMID 24947326, 2014). "Densitometry of relative RT-PCR EGFR tumor transcripts were significantly decreased compared to normal lung EGFR message, whereas transcripts for ALK were significantly increased in tumors compared to the corresponding normal tissue ALK message (n = 3)." (PMID 24423144, 2014). "Currently, the treatment’s choice is based on a careful assessment of tumor histology and, most importantly, of biological characteristics, specifically of the EGFR and ALK status." (PMID 25505694, 2014). "Third, midkine, a ligand that activates mammalian ALK, is produced by NF1−/− Schwann cells, present at elevated levels in NF1 patient skin and serum, and acts as a mitogen for NF1 tumor cell lines." (PMID 24278035, 2013). "The freshly isolated FC-IBC01 tumor cells served as the source of cells to analyze the effects of Crizotinib and to derive a new IBC cell line and xenograft model used for to assess ALK gene expression, and in vivo response to Crizotinib." (PMID 24102046, 2013). "In both cases, 1 fused signal was observed in the tumor cell nucleus, indicating the presence of RANBP2 and ALK gene rearrangement by unbalanced genetic rearrangement mechanism." (PMID 24034896, 2013). "Immunohistochemically, the tumour cells showed cytoplasmatic positivity for vimentin, smooth muscle actin (SMA), anaplastic lymphoma kinase (ALK), and focal positivity for desmin." (PMID 24024066, 2013).
tumor (continued). "While analyzing these skin lesions by H&E, we noticed the trichilemmal keratinization and strong expression of ALK and GLI1 within the tumours." (PMID 24163262, 2013). "Further experiments are needed to address the possibility of PTN mediating its effects via ALK in SCLC cells, the effects of PTN deletion on tumor growth, and the mechanism of PTN/PTPRZ1 autocrine regulation in NET cells." (PMID 23170925, 2012). "This and other oncogenic client proteins (e.g. B-RAF, C-RAF, ALK and CDK4) are depleted by 17-AAG in both animal tumours and patients." (PMID 22621282, 2012). "Immunohistochemically, tumor cells showed CD3+, CD45RO+, CD5-, CD7-, CD4-, CD8-, CD10-, CD20-, CD30-, CD79a-, CD138-, CD56-, granzyme B-, TIA-1+ and ALK-." (PMID 22931631, 2012). "It was, however, difficult to separate ALCL, ALK+, AITL and PTCL, NOS, and to assess the contribution of reactive cells within the tumour microenvironment." (PMID 21887344, 2011). "Despite the ALK+ phenotype, the patient had an aggressive course possibly related to CD56 expression by the tumour cells." (PMID 16623775, 2006). "Despite comprehensive diagnostic efforts, both ALK immunohistochemistry and FISH results were negative, leaving the tumor’s lineage and differentiation uncertain." (PMID 41560086, 2026). "Notably, we analyzed three different subgroups of mouse IHG-related models, driven by ALK, NTRK and ROS1, respectively, which have previously been stratified into the same tumor category." (PMID 41381884, 2026). "Increasing evidence indicates that oncogenic drivers, including EGFR, ALK, KRAS, MET, RET, and BRAF, actively shape the tumor immune microenvironment (TIME) by regulating antigen presentation, immune cell infiltration, cytokine signaling, metabolic programs, and immune checkpoint expression." (PMID 42079655, 2026). "The tumor cells were positive for CD163, ALK, phosphorylated ERK, and cyclin D1." (PMID 40361876, 2025). "The tumor specificity of the TERT rearrangement breakpoint may make it a better marker than a gene amplification, because the ALK copy-number gain plays against the normal diploid background of cfDNA derived from nonmalignant cells." (PMID 39760332, 2025). "Immunohistochemical analysis showed that the tumor cells of inflammatory myofibroblastoma strongly expressed vimentin, partially expressed desmin and ALK, and showed no expression of CD34 and CD117." (PMID 40548121, 2025). "We established a patient-derived xenograft (PDX) and in vitro model (designated PTCL-S1) of TP63-rearranged ALK-negative ALCL from the primary tumour site of a 55-year old Chinese woman." (PMID 40715645, 2025). "Non-target IgG and CDX0239 controls were utilized to demonstrate lack of non-target human IgG and humanized anti-ALK anti-tumor activity, respectively." (PMID 40813394, 2025). "The tumor showed no epidermal growth factor receptor (EGFR) expression or anaplastic lymphoma kinase (ALK) rearrangement and was characterized by bilateral pulmonary involvement without distant metastases." (PMID 40255775, 2025). "Although previous studies have reported increased tumor PD-L1 expression to be an unfavorable prognostic factor for NSCLC, the characteristics of the TIME and their prognostic values in ALK-rearranged NSCLC remain unclear." (PMID 40376302, 2025). "In kinase-addicted NSCLC, a reduction in tumor cell survival following EGFR- and ALK-directed therapy interventions could be counteracted by exposure to nonmalignant CAF populations or CAF-associated paracrine mediators." (PMID 40524253, 2025). "More intensive surveillance should be considered for high-risk features including positive or close resection margins, ALK-negative status, larger tumor size (> 5 cm), locally invasive behavior, or recurrent disease." (PMID 40234278, 2025). "Overexpression or fusion of ALK can reinstate ERK phosphorylation and sustain tumor proliferation, suggesting that ALK inhibitors may help overcome BRAFi resistance." (PMID 40873540, 2025).